HDAC8 (histone deacetylase 8)
Diseases named in the same sentence as HDAC8 in open-access papers (continued):
Sharing a sentence is not in itself a finding about the gene and the disease.
osteosarcoma (2 papers, 2023 to 2025). A usually aggressive malignant bone-forming mesenchymal neoplasm, predominantly affecting adolescents and young adults. "This study investigates the therapeutic potential of combining doxo with HDAC inhibitors, specifically Tas, an HDAC4 inhibitor, and PCI, a selective HDAC8 inhibitor, in osteosarcoma treatment." (PMID 40332124, 2025). "In contrast, HDAC8 has been shown to facilitate tumor proliferation, metastasis, and immune evasion in multiple cancer types, although its precise role in osteosarcoma remains unclear, necessitating further investigation." (PMID 40332124, 2025). "In addition, the expression levels of several other HDAC family members, such as HDAC2, HDAC3, HDAC5, and HDAC8 were also upregulated, suggesting a potentially redundant function of HDACs in osteosarcoma." (PMID 37457661, 2023). "Consequently, this study focused on the roles of HDAC4 and HDAC8 in osteosarcoma progression." (PMID 40332124, 2025). "In this context, the present study aimed to evaluate the therapeutic potential of combining doxo with the selective HDAC inhibitors, tasquinimod (Tas, targeting HDAC4) and PCI-34051 (PCI, targeting HDAC8), in SJSA-1 osteosarcoma cells." (PMID 40332124, 2025).
pulmonary arterial hypertension (2 papers, 2022 to 2023). Pulmonary arterial hypertension (PAH) is a group of diseases characterized by mean pulmonary artery pressure >20 mmHg and elevated pulmonary arterial resistance leading to right heart failure. "HDAC8 is upregulated in various tissues and cells of patients with pulmonary arterial hypertension (PAH)." (PMID 36231123, 2022). "HDAC8 takes part in pulmonary hypertension, fibrosis, and inflammation." (PMID 36231123, 2022). "In samples from patients with pulmonary arterial hypertension (PAH), HDAC1 and HDAC8 were observed to be increased." (PMID 38255639, 2023).
renal carcinoma (2 papers, 2023 to 2024). A carcinoma arising from the epithelium of the renal parenchyma or the renal pelvis. "Histone deacetylases class 1 (HDAC1, HDAC2, HDAC3, and HDAC8) are expressed ubiquitously in almost all types of cancer except renal cancer." (PMID 37345150, 2023). "Analysis of the CPTAC dataset revealed that the protein level of HDAC8 in renal cancer tissue was higher than that in nontumor renal tissue." (PMID 39073752, 2024).
Sepsis (2 papers, 2017 to 2020). Sepsis is defined as life-threatening organ dysfunction caused by a dysregulated host response to infection. "Taken together, these findings suggested that WK2-16 with HDAC8 inhibition could abrogate MMP-9 and IL-6 production, possibly providing a novel therapeutic strategy of sepsis and systemic inflammation." (PMID 28661460, 2017).
X-linked intellectual disability (2 papers, 2022 to 2024). An X-linked intellectual deficiency in which not enough information is known, reported or published to indicate whether a gene causes non-syndromic or syndromic presentations. "In recent years, HDAC8, a class I HDAC, has emerged as a promising target for different disorders, including X-linked intellectual disability, fibrotic diseases, cancer, and various neuropathological conditions." (PMID 36077415, 2022).
acute kidney injury (1 paper, 2024). Sudden and sustained deterioration of the kidney function characterized by decreased glomerular filtration rate, increased serum creatinine or oliguria. "Our study suggests that targeting histone deacetylase 8 could be a potential treatment for cisplatin‐induced acute kidney injury (AKI)." (PMID 39317961, 2024).
adult T-cell leukemia/lymphoma (1 paper, 2022). A peripheral (mature) T-cell neoplasm linked to the human T-cell leukemia virus type 1 (HTLV-1), adult T-cell leukemia/lymphoma is endemic in several regions of the world, in particular Japan, the Caribbean, and parts of Central Africa. "In adult T-cell leukemia/lymphoma (ATL), HDAC8 expression was driven by an oncogenic cascade of FRA-2/JUND and SOX4 transcription factor, and— together with other two activated genes, GCKR and NAP1—was proven to affect ATL cell growth." (PMID 35887172, 2022).
alcohol use disorder (1 paper, 2026). "HDAC8 is a histone deacetylase enzyme that plays a key role in the development of various diseases in humans, including cancers, neurodegenerative diseases, and alcohol use disorder." (PMID 41599354, 2026).
Alzheimer disease (1 paper, 2019). A progressive, neurodegenerative disease characterized by loss of function and death of nerve cells in several areas of the brain leading to loss of cognitive function such as memory and language. "A specific HDAC6 inhibitor ameliorated Alzheimer’s disease phenotypes, and an HDAC8 inhibition repaired scopolamine-induced learning and memory impairments in animals." (PMID 30669368, 2019).
astrocytoma (1 paper, 2008). "For class I, the highest median value observed was 2.87 (HDAC8 in low-grade astrocytoma) and the lowest median value was 0.62 (HDAC3 in astrocytoma grade III)." (PMID 18713462, 2008).
brain hemorrhage (1 paper, 2017). "It is worth noting that Hdac8 knockout mice exhibit perinatal lethality due to massive ossification defects in the skull, which lead to brain tissue herniation and brain hemorrhage, suggesting a specific role of HDAC8 in regulating skull morphogenesis rather than brain development." (PMID 28161493, 2017).
CHARGE syndrome (1 paper, 2020). CHARGE syndrome is a multiple congenital anomaly syndrome characterized by the variable combination of multiple anomalies, mainly Coloboma; Choanal atresia/stenosis; Cranial nerve dysfunction; Characteristic ear anomalies (known as the major 4 C's). "In one case, Rubinstein–Taybi syndrome (#S40, SMC1A gene) and Charge syndrome were suggested as the first diagnosis for a H46 with a variant in the HDAC8 gene." (PMID 32033219, 2020).
chromophobe carcinoma (1 paper, 2021). "For example, in RCC (including chromophobe carcinoma, ccRCC, and papillary cell carcinoma), low expression of HDAC1, HDAC2, HDAC3, HDAC8, HDAC10 and high expression of HDAC5, HDAC7, HDAC11 have longer survival time." (PMID 34308568, 2021).
cognitive decline (1 paper, 2025). "When focusing on X-linked genes, sex significantly moderated MCF2, HDAC8, SLC10A3, and FTX on tau tangle burden or cognitive decline in the DLPFC." (PMID 40166028, 2025). "By contrast, greater HDAC8 and SLC10A3 expression was associated with greater tau tangle burden and faster cognitive decline, respectively, in females only." (PMID 40166028, 2025).
colon adenocarcinoma (1 paper, 2022). "Retrieval of HDAC8 expression patterns in CRC included in TCGA and GTEx from the GEPIA database revealed the presence of elevated HDAC8 in colon adenocarcinoma and rectum adenocarcinoma." (PMID 36035205, 2022).
Constipation (1 paper, 2024). Infrequent or difficult evacuation of feces. "Constipation and GERD are more common in patients with variants in the NIPBL and SMC1A genes, visual impairment in NIPBL, SMC1A, and HDAC8, structural brain abnormalities in NIPBL, and sleep problems in NIPBL and SMC1A." (PMID 38673696, 2024).
Dystonia (1 paper, 2024). An abnormally increased muscular tone that causes fixed abnormal postures. "Prospective follow-up of this patient will help us further elucidate the association between the HDAC8 gene and dystonias." (PMID 38910710, 2024). "Since it is already known that single gene disorders, including SCN1A, SCN2A, KCNQ2, PRRT2, and pyridoxine deficiency, can result in isolated dystonia, we add CdLS5 (HDAC8 variation) to this expanding spectrum." (PMID 38910710, 2024). "It is already known that single gene disorders, including SCN1A, SCN2A, KCNQ2, PRRT2, and pyridoxine deficiency, can result in isolated dystonia; we add CdLS5 (HDAC8 variation) to this expanding spectrum." (PMID 38910710, 2024).
endometriosis (1 paper, 2024). The growth of functional endometrial tissue in anatomic sites outside the uterine body. "Here, we propose that the ERβ/HDAC8 axis is the key driver for the downregulation of endometrial stromal NMI to enhance endometriosis." (PMID 39125716, 2024). "Among them, Histone Deacetylase 8 (HDAC8) is aberrantly expressed in endometriosis compared to normal tissues." (PMID 39125716, 2024). "Therefore, the loss of endometrial stromal NMI expression, driven by the ERβ/HDAC8 axis, initiates the progression of endometriosis." (PMID 39125716, 2024). "Therefore, the combination of PCI-34051 and oleuropein might effectively suppress the ERβ/HDAC8 axis and consequently restore NMI expression in endometrial stromal cells, rendering them sensitive to IFNA-induced cell death signaling for endometriosis treatment." (PMID 39125716, 2024). "However, this study did not elucidate the role of HDAC8 in the progression of endometriosis." (PMID 39125716, 2024).
epileptic seizures (1 paper, 2023). "Although there have been no consistent reports of CdLS patients with HDAC8 variants and epileptic seizures, SMC1 annotated to CdLS 2 (MIM#301044) is also designated DEE 85 (MIM#301044)." (PMID 37645600, 2023).
fibrosis (1 paper, 2021). the formation of excess fibrous connective tissue in an organ or tissue in a reparative or reactive process. "Based on our results, we propose that HDAC8 induces cardiac fibrosis." (PMID 33959033, 2021).
fibrous dysplasia (1 paper, 2020). A genetic, non-inheritable disorder caused by osteoblastic differentiation defects that result in the replacement of bone marrow and trabecular bone by fibrous stroma and immature bone. "Another recent study found that upregulation of HDAC8 in fibrous dysplasia is associated with impaired osteogenesis, while HDAC8 inhibition promotes osteogenic differentiation of MSCs." (PMID 32025282, 2020).
generalized dystonia (1 paper, 2024). "We describe a de novo missense mutation in the HDAC8 gene and expand the phenotype of the HDAC8 gene associated with CdLS5 to include generalized dystonia." (PMID 38910710, 2024). "We report a CdLS5 with de novo missense mutation c.628G>C in the HDAC8 gene and a novel phenotype of generalized dystonia, further delineating the phenotypic spectrum." (PMID 38910710, 2024).
gingivitis (1 paper, 2025). A disorder involving inflammation of the gums; may affect surrounding and supporting structures of the teeth. "Additionally, a clinical study analyzing saliva samples reported downregulation of the histone deacetylase genes HDAC4, HDAC8, and HDAC10 in gingivitis, and HDAC4, HDAC6, HDAC8, and HDAC9 in periodontitis." (PMID 41228440, 2025).
glaucoma (1 paper, 2024). Increased pressure in the eyeball due to obstruction of the outflow of aqueous humor. "The novel small molecule H7E, an HDAC8 inhibitor, protected against glaucoma damage by inhibiting Müller glial activation and preventing retinal cell death from oxidative stress." (PMID 39458902, 2024).
hypogonadotropic hypogonadism (1 paper, 2023). Abnormal ovarian or testicular function due to insufficient hormonal stimulation from the hypothalamic-pituitary axis. "High infertility risk cryptorchid boys display hypogonadotropic hypogonadism, which, together with the diminished expression of histone deacetylases and increased expression of HDAC8 decrotonylase, indicates altered histone marks and, thus, a perturbed histone code." (PMID 37730534, 2023).
immune deficiency (1 paper, 2022). "In a humanized mouse model of immune deficiency, histone deacetylase 8 (HDAC8) inhibition elevated global and enhancer acetylation of H3K27, allowing HCC cells to generate T cell-trafficking chemokines and alleviating T-cell exclusion." (PMID 36119533, 2022).
influenza (1 paper, 2020). An acute viral infection of the respiratory tract, occurring in isolated cases, in epidemics, or in pandemics; it is caused by serologically different strains of viruses (influenzaviruses) designated A, B, and C, has a 3-day incubation period, and usually lasts for 3 to 10 days. "Additionally, miR-21-3p has been found to be down-regulated during H5N1 AIV and 2009 pandemic H1N1 influenza virus infection and could promote influenza virus replication by repressing the expression of HDAC8 gene in A549 cells." (PMID 33069243, 2020).
KBG syndrome (1 paper, 2020). KBG syndrome is a rare condition characterized by a typical facial dysmorphism, macrodontia of the upper central incisors, skeletal (mainly costovertebral) anomalies and developmental delay. "Whereas for NIPBL and RAD21 patients, KBG syndrome was the second most common diagnosis (top-five rank), 54.5% (18/33) and 66,7% (2/3), Rubinstein–Taybi syndrome appeared most frequently in SMC1A and HDAC8 patients, 50.0% (4/8) and 80.0% (4/5), respectively." (PMID 32033219, 2020).
metastatic melanoma (1 paper, 2023). A melanoma that has spread from its primary site to another anatomic site. "Next, we examined HDAC8 and HIF1A expression patterns in normal, primary, and metastatic melanoma samples." (PMID 36831463, 2023).
Miscarriage (1 paper, 2021). A pregnancy that ends at a stage in which the fetus is incapable of surviving on its own, defined as the spontaneous loss of a fetus before the 22th week of pregnancy. "HDAC8 expression is decreased in decidual macrophages from recurrent spontaneous miscarriage patients, and HDAC8 knockdown suppresses M2 marker genes via activating ERK signalling pathway in THP‐1‐derived macrophages." (PMID 34145738, 2021).
mucositis (1 paper, 2025). Mucositis is inflammation and damage of the mucous membranes lining the mouth and other parts of the gastrointestinal (GI) tract. "Butyrate, a key SCFA, has been shown to inhibit histone deacetylase 8 (HDAC8), suppress NF-κB–driven pro-inflammatory genes, and up-regulate tight junction proteins, leading to improved nutrient absorption and reduced chemotherapy-induced mucositis." (PMID 41002589, 2025).
myeloid leukemia (1 paper, 2024). A clonal proliferation of myeloid cells and their precursors in the bone marrow, peripheral blood, and spleen. "Three cell lines werestrongly dependent of HDAC8 (MV4–11, MOLM-13, and OCI-AML3),while the other three were HDAC8-independent myeloid leukemia celllines (HEL, SET-2, and THP-1)." (PMID 38113354, 2024).
non-small cell lung carcinoma (1 paper, 2022). A group of at least three distinct histological types of lung cancer, including non-small cell squamous cell carcinoma, adenocarcinoma, and large cell carcinoma. "Recent research suggests that EPAC2 induces cell apoptosis by mediating the expression of histone deacetylases 8 (HDAC8) in H1299 non-small cell lung cancer cells." (PMID 35011543, 2022).
oral squamous cell carcinoma (1 paper, 2023). "HDAC8 overexpression has been detected in oral squamous cell carcinoma (OSCC) tissues and its silencing was shown to significantly reduce cell proliferation and induce apoptotic cell death." (PMID 37887281, 2023).
osteoarthritis (1 paper, 2022). A noninflammatory degenerative joint disease occurring chiefly in older persons, characterized by degeneration of the articular cartilage, hypertrophy of bone at the margins and changes in the synovial membrane. "Furthermore, the knockdown of HDAC8 significantly increases the expression of the chondrogenic marker, SOX9, and greatly decreases the expression of degenerating marker, RUNX2, suggesting that HDAC8 can be targeted to treat osteoarthritis." (PMID 36231123, 2022).
Peritoneal Fibrosis (1 paper, 2023). Disorder characterized by a wide range of structural changes in PERITONEUM, resulting from fibrogenic or inflammatory processes. "Then we assessed the role and mechanism of HDAC8 in peritoneal fibrosis progression in mouse model of peritoneal fibrosis induced by high glucose peritoneal dialysis fluid by using PCI-34051." (PMID 36911746, 2023). "In this research, we focused on the role and mechanisms of HDAC8 in peritoneal fibrosis and discussed the mechanisms involved." (PMID 36911746, 2023). "In mouse model of peritoneal fibrosis induced by high glucose dialysate, administration of PCI-34051 (a selective HDAC8 inhibitor) significantly prevented the progression of peritoneal fibrosis." (PMID 36911746, 2023). "Treatment of PCI-34051 (20mg/kg/d) after injection of 4.25% glucose PDF significantly reduced these pathological changes, suggesting that HDAC8 is a key mediator of peritoneal fibrosis." (PMID 36911746, 2023). "Then we assessed the role and mechanism of HDAC8 in peritoneal fibrosis progression in mouse model of peritoneal fibrosis induced by high glucose peritoneal dialysis fluid (PDF) by using PCI-34051." (PMID 36911746, 2023). "Since cortactin is only expressed in the cytoplasm of cells, we hypothesized that HDAC8 regulated peritoneal fibrosis by participating in cytoplasmic protein regulation." (PMID 36911746, 2023). "In conclusion, we demonstrated that blockade of HDAC8 could prevent and reverse peritoneal fibrosis." (PMID 36911746, 2023). "As such, targeting HDAC8 might be a new strategy to lessen the severity of peritoneal fibrosis." (PMID 36911746, 2023). "Thus, inhibition of HDAC8 may be a potential therapeutic strategy for prevention and treatment of peritoneal fibrosis in long term PD patients." (PMID 36911746, 2023). "In this research, we demonstrated that inhibition of HDAC8 with PCI-34051 or siRNA suppressed EMT, apoptosis and M2 macrophage polarization, ultimately attenuated peritoneal fibrosis and peritoneal dysfunction." (PMID 36911746, 2023). "Epigenetics has been shown to play an important role in peritoneal fibrosis, but the role of histone deacetylases 8 (HDAC8) in peritoneal fibrosis have not been elucidated." (PMID 36911746, 2023). "We demonstrated that HDAC8 promoted the EMT of HPMCs via EGFR/ERK1/2/STAT3/HIF-1α, induced M2 macrophage polarization via STAT6 and PI3K/Akt signaling pathways, and ultimately accelerated the process of peritoneal fibrosis." (PMID 36911746, 2023). "However, the specific mechanism and target proteins of HDAC8 in regulating peritoneal fibrosis have not been revealed." (PMID 36911746, 2023).
peritonitis (1 paper, 2023). Inflammation of the peritoneum (tissue that lines the abdominal wall and covers most of the organs in the abdomen). "HDAC8 was highly expressed in the thickened peritoneum of long-term PD patients with PD-related peritonitis, and HDAC8 was co-expressed with α-SMA positive cells." (PMID 36911746, 2023). "We collected peritoneal tissue during catheterization initiation operations (n = 6) and refractory peritonitis-induced catheter migration (n = 6) and completed co-immunofluorescent staining of HDAC8 and α-SMA." (PMID 36911746, 2023). "We found that HDAC8 expressed highly in the peritoneum from patients with PD-related peritonitis." (PMID 36911746, 2023).
renovascular hypertensive (1 paper, 2021). "In addition, HDAC2 and HDAC8 expression levels are upregulated in renovascular hypertensive rats, while sodium valproate, a non-specific HDAC inhibitor, attenuates cardiac remodeling, confirming the involvement of HDAC2 and HDAC8 in cardiac remodeling." (PMID 33959033, 2021).
smooth muscle tumor (1 paper, 2017). A benign or malignant myomatous neoplasm arising from smooth muscle. "An immunohistochemical panel that includes CD10 and at least two smooth muscle markers such as desmin, caldesmon, and HDAC8 is helpful in the differential diagnosis of smooth muscle tumors from ESS." (PMID 28968994, 2017).